CRP (C-reactive protein)
Diseases named in the same sentence as CRP in open-access papers (continued):
Sharing a sentence is not in itself a finding about the gene and the disease.
dementia (continued). "To assess systemic inflammation as a potential pathway linking exposure to racism and dementia disparities, we investigated the mediating role of C-reactive protein (CRP), a systemic inflammation marker, and the moderating role of race/ethnicity on racialized disparities in incident dementia." (PMID 37066239, 2023). "When individuals are racialized as non-Hispanic Black and/or Hispanic, the effect of CRP on incident dementia risk is greater than expected had these individuals been racialized (and treated) as non-Hispanic White." (PMID 37066239, 2023). "In a previous study, participants with increased CRP concentration at baseline increased over 50% risk of developing dementia; while this association no longer remained significant after adjusting for possible confounding of CVD risk factors." (PMID 37593375, 2023). "Among minoritized participants (i.e., non-Hispanic Black and/or Hispanic), high CRP levels (> 75th percentile or 4.57mcg/mL) was associated with 1.27 (95%CI: 1.01,1.59) times greater risk of incident dementia than low CRP (<4.57mcg/mL)." (PMID 37066239, 2023). "CRP, as a representative acute-phase reactant, is regarded as an indicator of systemic inflammation.There is evidence that elevated CRP plays a crucial role in the development of cognitive dysfunction in both dementia and delirium." (PMID 37190623, 2023). "Elevated levels of circulating inflammatory markers such as IL-6, TNFα and CRP, induces the development of chronic low-grade inflammation which has been identified as a risk predictor for several diseases such as T2DM and dementia." (PMID 37720640, 2023). "O’Bryant and colleagues reported significantly decreased mean CRP levels in the AD group in relation to controls, whereas within the AD group elevated CRP levels significantly predicted higher (poorer) dementia severity (Clinical Dementia Rating Scales) scores." (PMID 37467176, 2023). "Meta‐analyses of relatively large samples across multiple countries have demonstrated associations between a limited number of peripheral inflammatory biomarkers including CRP and IL‐6 among others and all‐cause dementia, but not AD dementia." (PMID 37584418, 2023). "For example, some cross-sectional and longitudinal studies involving people without dementia found that higher levels of interleukin (IL)-6 and C-reactive protein (CRP) are associated with an increased risk for all causes of dementia and cognitive decline." (PMID 37168718, 2023). "We attribute these findings to the weak association between CRP and incident dementia among non-Hispanic Black participants, for which we have two possible explanations." (PMID 37066239, 2023). "As for inflammatory markers such as CRP, an important signaling molecule in inflammation that has effects on the brains or the periphery of people with dementia, which can explain why high CRP levels may be harmful." (PMID 35927253, 2022). "We hypothesized that quantitative differences in WBC populations, platelet counts, and/or CRP levels might be present between patients suffering from different types of dementia." (PMID 36358351, 2022). "In conclusion, we demonstrated that a higher WHR in midlife is linked to increased risk of dementia, and that this association is not explained by CRP or blood lipid levels." (PMID 36192662, 2022). "After adjustment for multiple comparisons, we found that only age, GCS, dementia, Charlson Index without dementia, pre-admission use of psychotropic drugs, CRP and NLR were associated with delirium in the univariable analysis." (PMID 35204633, 2022). "Previous meta-analyses showed that increased circulating interleukin(IL)-6 and C-reactive protein (CRP) levels were associated to higher risk of dementia from all causes, but not to AD." (PMID 35486344, 2022). "In terms of inflammation, elevated CRP levels were associated with slower reaction times, particularly in those without parental history of dementia." (PMID 33264710, 2021).
dementia (continued). "Present data are thus consistent with the original hypothesis that opening of the BBB by acute ischemic stroke may permit the elevated levels of IL-6 and CRP present in the brain tissue of dementia patients to be reflected in the serum." (PMID 32758167, 2020). "Older patients with dementia, and even old individuals without dementia, experience low-grade systemic inflammation characterized by increased high-sensitivity C-reactive protein (hs-CRP) levels associated with increased cognitive decline." (PMID 32979923, 2020). "In this study, a comparison of baseline characteristics between the groups before propensity score matching revealed that patients with greater age, lower serum albumin levels, higher C-reactive protein levels, and severe dementia were more likely to receive TPN." (PMID 31577813, 2019). "Studies have shown that patients with dementia had higher CRP levels than controls." (PMID 31475471, 2019). "In this cohort study, data from 2656 members of the Framingham Heart Study offspring cohort (Generation 2; August 13, 1971-November 27, 2017) were evaluated, including longitudinal measures of serum C-reactive protein (CRP), diagnoses of incident dementia including AD, and brain volume." (PMID 30646251, 2018). "After controlling for confounding risk factors (higher age, dementia, disability on admission, increased CRP), delirious patients in our cohort had not a worse outcome, compared to similar patients without delirium." (PMID 28828209, 2017). "Linking familial risks with early plasma indicators of AD and dementia (C-reactive protein, interleukin-6 and α1-antichymotrypsin, for example) with plasma DHA status may also help to identify those with the most potential for benefit from supplementation." (PMID 26901223, 2016). "Other biomarkers of risk to dementia, such as the presence of ApoE4 and inflammatory markers (IL6, CRP), may be associated with a steeper decline on cognitive status or greater neuronal loss." (PMID 25685779, 2015). "CRP is a marker of inflammation and has been shown to predict cognitive decline and dementia." (PMID 25996285, 2015). "When comparing ApoE ε4 allele carriers and non-carriers regardless of dementia status, subjects with one or two ε4 alleles presented with significantly lower CRP levels." (PMID 24804776, 2014). "Additionally, we compared the performance of the CRP and GDF15 DNAm scores to that of their plasma protein counterparts and determined whether the DNAm associations extended to near‐ and long‐term dementia risk in two independent cohort studies." (PMID 41274863, 2025). "Finally, the MMSE score was used in addition to CRP to assess age-related dementia changes." (PMID 40955269, 2025). "The UK Biobank, which includes over 500,000 participants with extensive cognitive, imaging, and inflammatory marker data, has shown that hsCRP is associated with increased risk of cognitive decline and dementia in RA patients, though it does not differentiate CRP isoforms." (PMID 40943152, 2025). "Finally, we related DNAm/plasma CRP and GDF15 to dementia risk in two external cohorts." (PMID 41274863, 2025). "Despite these limitations, the current study demonstrates that epigenetic proxies of CRP and GDF15 exposure reflect the activation of immune/inflammation‐related pathways associated with accelerated brain atrophy, cognitive decline, and long‐term dementia risk." (PMID 41274863, 2025). "Our results suggest that elevated levels of systemic inflammation are associated with a higher risk of dementia in US adults, and high CRP levels (≥4.73 μg/mL) explain a small proportion of the racial disparity in dementia incidence between minoritized US adults and non-Hispanic white adults." (PMID 39003383, 2024). "The rise in levels of C-reactive protein may be a response to the disease process rather than a cause for dementia/AD." (PMID 38378514, 2024).
dementia (continued). "However, consistent with the present absence of a CRP-dementia association, several studies have not demonstrated an association between CRP levels and subsequent all-cause dementia incidence." (PMID 38706574, 2024). "In a nationally representative sample of older adults in the United States, we observed a 23% greater risk of incident dementia among those with high versus low CRP, and this association was stronger among Hispanic and non-Hispanic white participants than among non-Hispanic Black participants." (PMID 39003383, 2024). "Given the potential decade-long neuropathological development of dementia, multiple CRP measurements over prolonged time periods (>20 years) will be required in future research to clarify the potential U-shaped pattern of CRP trajectories over the course of dementia." (PMID 38706574, 2024). "Similarly, the risk of 6-year incident dementia for non-Hispanic white participants with high CRP was 1.19 (95% CI: 0.98, 1.45) times higher than those with low CRP, but this finding was not statistically significant." (PMID 39003383, 2024). "In this model the presence of CRP is necessary, but not sufficient, to cause dementia." (PMID 37467176, 2023). "Age, dementia at admission, Charlson Comorbidity Index, and several laboratory findings, such as white blood cell counts, lactate dehydrogenase level, total protein level, albumin level, blood urea nitrogen level, C-reactive protein level, and fibrinogen level differed between the two groups." (PMID 37240566, 2023). "Similarly, the risk of 6-year incident dementia for non-Hispanic White participants with high CRP was 1.25 (95% CI: 1.04, 1.50) times higher than those with low CRP." (PMID 37066239, 2023). "Elevated hsCRP has also been reported in older adults with corpus callosum alterations, whereas higher systemic inflammation levels may be linked to lower microstructural integrity in the corpus callosum of non-demented elderlies—thus raising questions on studies for dementia and CRP." (PMID 37873776, 2023). "Moreover, a significant non-linear relationship between CRP and risk of dementia (p for non-linearity < 0.001) and MDD (p for non-linearity = 0.001) was observed." (PMID 38071240, 2023). "Moreover, we discovered strong U-shaped associations of C−reactive protein (CRP, P for non-linearity = 5.5E-09), and HbA1c (P for non-linearity = 0.007) with the risk of incident dementia, with nadirs at 2.5 mg/L, 34 mmol/mol, respectively." (PMID 35927253, 2022). "Critically, current evidence suggests that adipose tissue is a major contributor to circulating inflammatory markers such as C-reactive protein (CRP) and interleukin-6 (IL-6), and may underline the association between adiposity and cognitive decline and dementia." (PMID 35436329, 2022). "The CRP and IL-6 were associated with all-cause dementia rather than AD." (PMID 36293430, 2022). "One SD higher CRP, but not lipid biomarkers, was associated with a lower risk of dementia." (PMID 36192662, 2022). "After removing the outliers, CRP was no longer associated with AD or dementia, and others." (PMID 34386016, 2021). "Adverse prognostic factors included male sex; a Charlson comorbidity index greater than 5; elevated levels of prognostic markers (CRP, NLR, and D-dimers); and the presence of dementia or chronic heart disease." (PMID 40431642, 2025). "As dementia subtypes are combined for all-cause dementia outcomes, current and previous null findings for all cause-dementia could be due to potential non-significant CRP-AD associations masking existing associations between CRP and other dementia subtypes (e.g., VAD)." (PMID 38706574, 2024). "Several epidemiological studies consistently demonstrate a significant association between systemic inflammatory markers, namely C-reactive protein (CRP) and tumor necrosis factor-α (TNF-α), and cognitive impairment or dementia." (PMID 39114530, 2024).
dementia (continued). "Hence, this could represent the association between elevated CRP levels during chronic inflammatory conditions, increased BBB permeability, and subsequent infiltration of CRP in the brain as potential cause of Alzheimer’s disease and dementia." (PMID 36776896, 2023). "Risk factors for hypernatraemia at presentation included age, institutionalization, congestive heart failure, dementia, higher SARS-CoV-2 Ct value, white cell count, C-reactive protein and lower eGFR and albumin levels (p < 0.001 for all)." (PMID 36769690, 2023). "Inflammatory markers, such as C-reactive protein (CRP) and interleukin-6 (IL-6), have been found to be elevated in individuals with MCI and dementia." (PMID 37509024, 2023). "Thus, CRP could possibly play a role in the differential diagnosis of dementia." (PMID 36358351, 2022). "Thus, CRP in conjunction with immunophenotyping of immune cell subsets might emerge as potential serological and cellular biomarkers in the differential diagnosis of dementia." (PMID 36358351, 2022). "The inflammatory markers serum amyloid A (SAA) and C-reactive protein (CRP) were also found to be significantly increased in MSA and Parkinson’s disease with dementia (PDD) when compared to healthy volunteers and patients affected with PD without dementia." (PMID 33809527, 2021). "YKL-40 correlated with the concentrations of other markers (t-tau and Aβ1-42/Aβ1-40), the severity of dementia as reflected by the MMSE score, and the parameters of inflammation (C-reactive protein and percentage of neutrophils)." (PMID 34589009, 2021). "It is proved in the present study that expression levels of IL-6, CRP and TNF-α proteins in VD patients are higher than those in the normal population on one hand, and positive correlated to dementia degrees on the other hand." (PMID 34475939, 2021). "The results by using univariate analysis presented that there were significantly differences in age, senile dementia, hypothyroidism, WBC, PCT, C-reactive protein (CRP), and prolonged bed rest between the two groups (P < 0.05)." (PMID 34901268, 2021). "In these parameters, ACPA, SHS, HAQ-DI, CRP, PS-VAS, N.Com, dementia treated, and GCS administration demonstrated significant correlation with aging, whereas after the effect of age was corrected, relationships were re-evaluated with MLR." (PMID 32588031, 2020). "Inflammatory proteins in blood, notably C reactive protein (CRP) and IL6, are elevated several years before the clinical onset of dementia in several studies." (PMID 29520228, 2018). "Previous findings have shown higher peripheral levels of inflammatory markers such as IL-6, CRP, TNF-α in patients with dementia compared to controls." (PMID 28798686, 2017). "Improving the sample size of the study is necessary to confirm the relationship between IL-6, Hs-CRP, and preclinical AD, such as memory impairment and MCI in middle-aged subjects and dementia in subjects with higher age." (PMID 26682220, 2015). "Comparing with the eligible patients, the subjects who were excluded due to development of dementia within 1 year were significantly greater in UPDRS-III score, and had similar CRP levels, while they had elderly onset and took lower LEDs (data not shown)." (PMID 26308525, 2015). "Decreased in patients with dementia. miR-223 level correlated with Mental State Examination (MMSE) scores, Clinical Dementia Rating (CDR) scores, magnetic resonance spectroscopy (MRS) spectral ratios, and serum concentrations of IL-1b, IL-6, TNF-α, and CRP." (PMID 40943171, 2025). "We found that IL6, REN, CRP, and ACE play a role in dementia (purple spheres)." (PMID 40699836, 2025). "This has led researchers to consider CRP not just a marker but a possible trigger of AD-like dementia." (PMID 40943152, 2025). "Furthermore, we measured C-reactive protein (CRP) and interleukin-6 (IL-6), well-established markers of systemic inflammation known to be elevated in POD and dementia." (PMID 40218194, 2025).
dementia (continued). "In the current study, lifestyle behaviours predicted CRP levels, suggesting that the non-significant mediation through CRP is likely to be attributable to the absence of a predictive role of CRP in dementia." (PMID 38706574, 2024). "We found that when comparing the minoritized group to the non-Hispanic white group, the mediating effect of CRP on incident dementia accounted for 3% (95% CI: 0%, 6%) of the disparity, and the proportion due to interaction accounted for 15% (95% CI: 2%, 28%)." (PMID 39003383, 2024). "We found that when comparing the minoritized group to the non-Hispanic white group, the mediating effect of CRP on incident dementia accounted for 4% (95% CI: 0%, 6%) of the disparity, and the proportion due to interaction accounted for 15% (95% CI: 1%, 29%)." (PMID 39003383, 2024). "Our study, for the first time, investigated and discovered a non-linear relationship between CRP levels and incident dementia." (PMID 38071240, 2023). "In CSF from 300 people over the age of 60, people without dementia also show higher inflammation and increased C-reactive protein (CRP) in the blood of people with AD." (PMID 37600508, 2023). "There was a significant effect of LRG levels on the presence of dementia (p = 0.019), while those of CRP levels or CCI were not significant." (PMID 36812242, 2023). "We found that when comparing the minoritized group to the non-Hispanic White group, the mediating effect of CRP on incident dementia accounted for 3% (95% CI: 0%, 6%) of the disparity, and the proportion due to interaction accounted for 14% (95% CI: 2%, 25%)." (PMID 37066239, 2023). "These predictors entered the stepwise multivariable model, which retained delirium as the strongest independent predictor of death/admission to ICU, together with only three other variables: Charlson Index without dementia, CRP and NLR." (PMID 35204633, 2022). "We observed neither statistically significant differences regarding total WBC populations, platelet counts, neutrophil-to-lymphocyte ratio and platelet-to-lymphocyte ratio, nor CRP levels between the control group and the five dementia groups." (PMID 36358351, 2022). "In the univariable model, after adjustment for multiple comparisons, the statistically significant predictors of delirium development were: age, GCS, Charlson Index without dementia, dementia, pre-admission use of psychotropic drugs, CRP and NLR." (PMID 35204633, 2022). "After adjustment for multiple comparisons, age, GCS, Charlson Index without dementia and a number of laboratory variables (hemoglobin, white blood cell count, neutrophils, eGFR, LDH, D-dimer, CRP, NLR) were found to be associated with the composite outcome." (PMID 35204633, 2022). "In turn, delirium was the strongest independent predictor of death/admission to ICU (composite outcome), followed by Charlson Index (not including dementia), CRP, and neutrophil-to-lymphocyte ratio." (PMID 35204633, 2022). "Although two recent MR studies have demonstrated no causal association between C‐reactive protein (CRP), a broad marker of systemic inflammation, and dementia diagnosis, the potential causative associations between serum inflammatory cytokines and dementia diagnosis remain unknown." (PMID 31328178, 2018). "The 2656 individuals who completed at least 2 CRP measurements and did not have dementia at the time of their last CRP measurement were a mean (SD) age of 61.4 (9.4) years (eFigure 1 in the Supplement)." (PMID 30646251, 2018). "Variables such as medical history of aspiration pneumonia and dementia, use of dentures, NT-proBNP, TLC, BUN, CRP, albumin, transthyretin, MMSE, handgrip strength, prehospital MSAS and MSAS, MPT, and prehospital BI and BI, were entered into a multivariate model." (PMID 27898735, 2016). "In other studies, low-grade inflammation as reflected by serum CRP concentrations was found in subjects with cognitive dysfunction without dementia and in patients with non-amnestic MCI." (PMID 26578953, 2015).